EGF (epidermal growth factor)
Diseases named in the same sentence as EGF in open-access papers (continued):
Sharing a sentence is not in itself a finding about the gene and the disease.
breast carcinoma (continued). "Mechanistically, ADAM17 on breast cancer cells has been found to cleave and release epidermal growth factor (EGF) family members from the cell surface, which then act through EGF receptor (EGFR) to promote tumor cell proliferation and invasion." (PMID 27738494, 2016). "We modulated the invasiveness of breast cancer cells by the introduction of a 3D EGF gradient within the tumor-stroma platform." (PMID 27678304, 2016). "Abolition of SRC kinases-mediated EGFR phosphorylation has been shown to inhibit EGF-induced proliferation and/or transformation in many types of cancer cells, such as breast cancer cells and cervical cancer cells." (PMID 26849234, 2016). "In the MCF-7 breast cancer cell line, resveratrol was found to inhibit EGF-induced EMT via inhibition of the EGF-mediated Erk pathway activation." (PMID 27231938, 2016). "We clearly identified ‘biological’ EMT of EGF-stimulated breast cancer cells by using wound healing or a matrigel invasion assay." (PMID 27829223, 2016). "Both EGF-induced PD-L1 expression and ectopic PD-L1 expression were significantly reduced in basal-like breast cancer (BLBC) cells." (PMID 27572267, 2016). "The infiltrating T-lymphocytes in human breast cancer can produce EGF and analysis of breast tumor explants revealed that EGF is also produced by TAMs." (PMID 28053982, 2016). "In breast cancer, palmitoylation has been shown to control the function of commonly dysregulated genes including estrogen receptors, the epidermal growth factor (EGF) family of receptors, and cancer stem cell markers." (PMID 28721385, 2016). "We also demonstrate that epidermal growth factor (EGF) stabilizes PD-L1 via GSK3β inactivation in basal-like breast cancer." (PMID 27572267, 2016). "In our study, the corresponding canonical cancer pathways in the HBL tumor transcriptome are GBM, Her-2 breast cancer, EGF and ERBB signaling (EGFR), Wnt-β-catenin signaling (Wnt), STAT3 and JAK/STAT signaling (JAK/STAT), and mTOR signaling pathways (mTOR)." (PMID 27910913, 2016). "Until now, limited knowledge was concerning the regulation of MICAL1 function by EGF signaling in breast cancer cells." (PMID 27430308, 2016). "Our results showed that the migratory and invasive ability of breast cancer cells induced by EGF or FBS stimulation decreased significantly after MICAL1 silencing in vitro." (PMID 27430308, 2016). "For example, micro-needles filled with Matrigel® and EGF inserted into the mouse fat pads attracted breast cancer cells to the site of injection." (PMID 27678304, 2016). "EGF signaling is up-regulated in human cancers, including approximately 25% of breast cancer cases, as well as subsets of ovarian, lung, gastric and salivary gland tumors." (PMID 27341132, 2016). "Breast cancer cells were serum deprived for 24 h, followed by stimulation with EGF for varying amounts of time." (PMID 26673822, 2016). "Serum-starved ERBB2-positive SKBr3 breast cancer cells were exposed to EGF or heregulin (HRG) to activate HER2 through EGFR/HER2 and HER2/HER3 signalling routes, respectively." (PMID 27402251, 2016). "A subset of the EGF‐inducible lncRNAs we identified correlated with clinical outcome of breast cancer patients." (PMID 27485121, 2016). "A novel insight regarding the molecular mechanisms of breast cancer metastasis is that EGF-induced EMT can occur via the Smad2/3-Snail signaling pathway in MCF-7 breast cancer cells." (PMID 27829223, 2016). "On a global level, we observed enhanced invasiveness of the breast cancer tumor front when stimulated with EGF." (PMID 27678304, 2016). "Recent studies have indicated a prominent role of paracrine epidermal growth factor (EGF) in driving breast cancer metastasis." (PMID 27829223, 2016). "Co-treatment of HER2-positive breast cancer cells with both EGF and AICAR resulted in significantly increased survival compared to AICAR treatment alone." (PMID 26143491, 2015).
breast carcinoma (continued). "Exosomes from HEK293 cells stably expressing EGF or EGFR peptide have also been studied as therapeutic agents by targeting breast cancer cells expressing high levels of EGFR (such as the HCC70 breast carcinoma cell line)." (PMID 26601108, 2015). "Our previous results have shown that Arf6 exerts pro-migratory action in breast cancer cells after EGF stimulation." (PMID 25678857, 2015). "For example, it is known that breast cancer cells grow in a disorganized fashion on reconstituted basement membrane assays by employing int β1 and epidermal growth factor (EGF)-dependent signaling pathways." (PMID 26631983, 2015). "The findings in this study present a novel mechanism for EGF-induced invasion and metastasis and have important implications for the development of effective breast cancer treatment strategies." (PMID 26599012, 2015). "We have shown that EGF- and hypoxia-induced transitions respond differently to treatment with chemical inhibitors (presented individually and in combinations) in these breast cancer cells." (PMID 25975820, 2015). "Another agent, (+)-aeroplysinin-1 (a natural metabolite from a type of marine sponge), abolished the proliferative effect of EGF on breast cancer cells and inhibited the ligand-induced endocytosis of the EGFR in vitro." (PMID 26258011, 2015). "We found that PYK2 is activated by both EGF and heregulin (HRG) in breast cancer cells, and positively regulates EGF/HRG-induced cell spreading, migration and invasion." (PMID 26084289, 2015). "Our results are also interesting in light of a previous study showing that PTK6 promotes p38 MAPK activation, subsequent Cyclin D1 expression and migration in the context of heregulin- or EGF-stimulated breast cancer cells." (PMID 26084280, 2015). "In the context of growth factor signaling, relative abundance of subsets of EGF-regulated miRNAs in breast cancer models have been shown to correlate with the abundance of miRNAs in breast cancer patients." (PMID 26287249, 2015). "In MDA-MB-231 breast cancer cells stably overexpressing H19, EGF strongly activated EGFR, Akt and Erk compared to parental cells." (PMID 26353930, 2015). "In a murine mammary carcinoma model, CSF-1 produced by tumor cells stimulated tumor macrophages to produce epidermal growth factor (EGF) which stimulated cancer cell chemotaxis and microvessel intravasation." (PMID 26317041, 2015). "The focus of this study was to determine the mechanism through which EGF regulates E-cadherin distribution in breast cancer cells, which is regarded as the first step of EMT." (PMID 25678857, 2015). "EGF stimulation and hypoxic tumour environments are both thought to be clinically-relevant drivers of breast cancer progression in vivo." (PMID 25975820, 2015). "In fact, it is reported that GEP100, a GEF for Arf6, links EGF/EGFR signaling to Arf6 activation to induce invasive activities of breast cancer cells." (PMID 25779663, 2015). "To further understand the timely cascade of regulation of EGF in breast cancer, we studied the time points of peak activation of the TGs, (from differential expression data) the TFs and the miRNAs, the last two were computed from NCA." (PMID 26763900, 2015). "Collectively, these results suggest that PYK2 affects different migratory and invasive pathways in breast cancer cells in response to either EGF or HRG stimulation, but most profoundly affects the MAPK and STAT3 pathways." (PMID 26084289, 2015). "Despite the fact that EGF signaling stimulates EMT of breast cancer cells, the effect of Arf6 on internalization of E-cadherin of breast cancer cells under EGF treatment remains to be determined." (PMID 25678857, 2015). "Together, these evidences suggest that Anxa2 is required for EGF-induced activation of STAT3 in breast cancer cells." (PMID 26307676, 2015). "The crosstalk between estrogen, IGF-I, and EGF signaling pathways and its involvement in endocrine resistance is well documented in breast cancer." (PMID 26258011, 2015).
breast carcinoma (continued). "While resulting in a common phenotype, EGF and hypoxia induced subtly different signalling systems in breast cancer cells." (PMID 25975820, 2015). "To demonstrate the consequences of this, we tested and compared the standard NCA algorithm with the ISNCA using 100 network configurations and microarray data obtained from breast cancer cells treated with EGF." (PMID 26537518, 2015). "EGF signaling cascade partially converge on ERα in breast cancer cells where it provides for an additional survival pathways." (PMID 26215677, 2015). "In this study, we observed that EGF induces EMT of breast cancer cells along with constantly tyrosine phosphorylation of Anxa2." (PMID 26307676, 2015). "This loss of spindle-shape morphology with BAPTA-AM was also seen in breast cancer cells where this chelator promoted N-cadherin inhibition thereby preventing the epithelial-mesenchymal transition induced by EGF." (PMID 25627260, 2015). "Immunoblotting and immunofluorescence assays showed that transfection breast cancer cells with Arf6-T27N or Arf6 siRNA suppressed EGF-induced E-cadherin internalization." (PMID 25678857, 2015). "The miRNA let-7d-5p showed a peak repressing activity around 2 h after EGF treatment and it is aberrantly expressed in breast cancer cells in previous study." (PMID 26763900, 2015). "To assess the effect of EGF on E-cadherin internalization in breast cancer cells, we treated MCF-7 cells with EGF, and measured internalized E-cadherin levels by internalization assays." (PMID 25678857, 2015). "To increase our understanding on the role of EGF in breast cancer, we performed functional annotation of the TGs and TFs in the integrated network using functional annotation tool DAVID." (PMID 26763900, 2015). "Collectively, these results suggest that β4 integrin enables the physical recruitment and subsequent activation of FAK, which promotes AKT and p38MAPK signaling in an EGF/Src dependent manner, thereby regulating breast cancer malignancy." (PMID 26549523, 2015). "Knockdown of PDK1 inhibits spontaneous migration and epidermal-growth-factor-induced chemotaxis in breast cancer cells." (PMID 26684827, 2015). "In this study, authors found that EGF-induced AKT activation was dependent on calmodulin in the majority of human breast cancer cell lines." (PMID 25627260, 2015). "The activation of ErbB receptors by epidermal growth factor (EGF) or heregulin (HRG) in the MCF7 breast cancer cell line exemplifies the impact of such transient or sustained signalling on cell fate." (PMID 25885578, 2015). "It confers a potent pro-invasion, pro-metastatic phenotype when expressed in breast cancer cells by potentiating their chemotactic invasion/migration response to EGF and by promoting discohesive cell motility." (PMID 26112005, 2015). "Taken together, these results demonstrated that Arf6 activation is required for EGF-induced E-cadherin internalization in breast cancer cells." (PMID 25678857, 2015). "In MCF-7 breast cancer cells epidermal growth factor (EGF) induces cell proliferation, whereas heregulin (HRG)/neuregulin (NRG) induces irreversible phenotypic changes accompanied by lipid accumulation." (PMID 25643809, 2015). "Targeting of EGF/IGF signaling pathway components has been characterized as a promising approach for breast cancer treatment." (PMID 26258011, 2015). "In the present review therefore, we will discuss in depth how IGF and EGF signaling participate in breast cancer pathogenesis and progression to endocrine resistant disease." (PMID 26258011, 2015). "In this context, it is worthwhile mentioning that down-regulation of 24 miRs preceded and instigated massive up-regulation of oncogenic mRNAs in breast cancer cell lines, upon EGF stimulation." (PMID 26440147, 2015).
breast carcinoma (continued). "Taken together, our data reveals the molecular mechanism through which an intrinsic tyrosine phosphorylation cascade of the EGF/Src-mediated β4 integrin/FAK complex is involved in the development of breast cancer malignancy." (PMID 26549523, 2015). "We have thus investigated the role of PBX1 in mediating EGF signalling in ERα-positive breast cancer cell lines using genome wide-analyses including microarray and ChIP-seq." (PMID 26215677, 2015). "Results showed that stable PTPH1 expression in T47D breast cancer cells decreases levels of endogenous and EGF-induced tyrosine phosphorylation of EGFR at Y1173 (p-EGFR/Y1173)." (PMID 26079946, 2015). "Our results demonstrate that PBX1 is required to direct EGF-ERα signalling at the chromatin level in breast cancer cells." (PMID 26215677, 2015). "Signalling through EGFRs is a well-established driver of breast cancer progression, and EGF is also known to stimulate EMT in some cells." (PMID 25975820, 2015). "We observed that knockdown of Gi1/2/3 not only clearly reduced the growth rate of breast cancer cells, but also significantly diminished their invasion ability in response to EGF, bFGF, IGF-1 and FBS." (PMID 24521094, 2014). "We previously showed that DGKα is necessary for matrix invasion promoted by Epidermal Growth Factor (EGF) or Hepatocyte Growth Factor (HGF) in MDA-MB-231 breast carcinoma cells." (PMID 24887021, 2014). "We have shown that the BRK substrate Sam68 (Src associated during mitosis, 68 kDa) is an effector of EGF stimulation and that BRK contributes to Sam68 phosphorylation in the EGF-treated breast cancer cells." (PMID 24523872, 2014). "Growth factor stimulation appears to be a part of this “crosstalk” as epidermal growth factor (EGF) leads to epitheliomesenchymal transition-like changes in human breast cancer cells including upregulation of vimentin and downregulation of E-cadherin." (PMID 25140302, 2014). "While these studies on nicotine mediated induction of SCF are relevant to NSCLC in smokers, there are reports suggesting that EGF can also induce SCF in breast cancer cells." (PMID 25401222, 2014). "In the case of breast cancer, the EGF is thought to be secreted by macrophages recruited in a paracrine loop by the tumour, but for other attractants and cell types the sources of chemotactic signals are not known." (PMID 25313567, 2014). "Growth factors such as insulin like growth factor-I (IGF-I) and epidermal growth factor (EGF) represent important signaling molecules in breast cancer." (PMID 24779681, 2014). "Previous studies have shown that HER2, an epidermal growth factor (EGF), is detected in ~25% breast cancer patients, and is associated with a poor prognosis." (PMID 25202398, 2014). "We previously showed that the ability of BRK to phosphorylate its endogenous substrate Sam68 in breast cancer cells was significantly enhanced by stimulation with epidermal growth factor (EGF)." (PMID 24523872, 2014). "Previous literature has demonstrated that Mcl-1 is a downstream target of epidermal growth factor (EGF) in many different types of cancer, including breast cancer." (PMID 24971890, 2014). "RGS16 locus is a site of genomic instability in (50% of 222) primary breast tumors and knockdown of RGS16 in breast cancer cell lines increases Epidermal Growth Factor (EGF) and Fetal Bovine Serum (FBS) initiated proliferation." (PMID 25568667, 2014). "Proliferation of breast cancer cells requires signals from growth factors such as estrogen and epidermal growth factor (EGF)." (PMID 25260534, 2014). "For example, a regulatory module consisting of the TFs EGR4, FRA-1, FHL2 and DIPA promotes proliferation in breast cancer cells in response to epidermal growth factor (EGF)." (PMID 24416123, 2014).
breast carcinoma (continued). "Basal like cancer is a molecular defined category of breast cancer with expression of unique set of genes involving epidermal growth factor (EFGR), basal cytokeratins (CK) 5/6, proliferation gene clusters and low expression of hormone and Her2neu genes." (PMID 24581278, 2014). "We stimulated SKBR3 breast cancer cell lines with EGF and observed peak activation of EGFR signalling at 5 minutes." (PMID 24523872, 2014). "For example, treatment of human breast cancer T47D cells with the MEK inhibitor U0126 in combination with the phosphoinositide 3-kinase/Akt inhibitor wortmannin synergistically suppressed EGF-induced ERK activation relative to treatment with U0126 alone." (PMID 24957684, 2014). "Previous literature has demonstrated that Mcl-1 is a downstream target of EGF in many different types of cancer, including breast cancer." (PMID 24971890, 2014). "Studies of breast cancer have revealed that TAMs are rich sources of epidermal growth factor (EGF), MMPs, and pro-angiogenic factors such as VEGF-A." (PMID 24567915, 2014). "In murine breast cancer models, IL-4 secretion by CD4+ Th2 cells activate tumor-associated macrophages (TAM) to facilitate pulmonary metastasis mediated by secretion of EGF." (PMID 25208941, 2014). "The involvement of EGFR in Prl-R signaling is supported by previous findings of the interplay between EGF and Prl in breast cancer cells." (PMID 24695557, 2014). "Because Akt and ERK1/2 signaling is required for cell growth and migration in response to growth factors, based on above observations, we reasoned that Giα proteins are involved in growth and invasion of breast cancers in response to EGF, bFGF, IGF-1 and FBS." (PMID 24521094, 2014). "Western blot analysis revealed that PIAS1 became phosphorylated on Ser90 in response to EGF or Heregulin in various breast cancer cell lines, including MDA-MB231, BT-20, BT-474 and HCC-1954." (PMID 24586797, 2014). "In breast cancer, EGF, which binds to the ErbB receptor tyrosine kinase family, has been shown to play a role in the invasion and metastasis of breast cancer." (PMID 23527039, 2013). "RT alone, however, has not yielded ideal clinical outcome and it is often associated with increased production of EGF and VEGF that contributes to radio-resistance by activating growth factor mediated pathways in squamous and mammary carcinoma cells." (PMID 24138843, 2013). "The effect of DPDIM on the survival of EGF induced breast cancer cells were further assessed by soft agar colony forming assay." (PMID 23555785, 2013). "Antibody-based, affibody-based, or EGF-based molecular probes for EGFR imaging of breast cancer have also been under active investigation." (PMID 23533377, 2013). "It has been suggested, for example, that reporter labeled EGF can activate the EGFr signaling pathway in breast cancer xenografts." (PMID 23331017, 2013). "Exogenous factors like EGF and LPA have been widely implicated as promoters of breast cancer cell invasion and metastasis by regulating signals that control cell motility." (PMID 23527039, 2013). "GPER has been shown to modulate ERK1/2 and Akt activity, which is dependent upon trans-activation of the epidermal growth factor (EGF) receptor via release of heparin-bound EGF (HB-EGF) in breast cancer cells." (PMID 23840305, 2013). "The data presented above showing that BCAR3 regulates the cytoskeletal response of invasive breast cancer cells to EGF thus provide a second point of convergence between BCAR3 and intracellular signaling pathways that control tumor cell motility and invasion." (PMID 23762409, 2013). "The “combined stimulation” approach is supported by published findings demonstrating coregulatory intracellular interactions existing between TNFα-, estrogen-, and/or EGF-mediated pathways in breast cancer and in other malignancies." (PMID 24369447, 2013).